SLC7A11 (solute carrier family 7 member 11)
Diseases named in the same sentence as SLC7A11 in open-access papers (continued):
Sharing a sentence is not in itself a finding about the gene and the disease.
cancer (continued). "Erastin, an SLC7A11 inhibitor, sensitizes radiotherapy resistant NSCLC cancer lines." (PMID 34830482, 2021). "Importantly, we verified a toxic gain-of-function mechanism of toxicity based on selenide toxicity, as preemptive KO of SLC7A11, while also abrogating selenoprotein production similarly to SEPHS2 KO, prevented the toxicity of SEPHS2 KO in cancer cells." (PMID 32709924, 2020). "In cancer cells, BAP1 removes monoubiquitin from ubiquitinated H2A at lysine 119 (H2Aub) on the SLC7A11 promoter to suppress its expression in cells treated with erastin but not RSL3, and this effect does not require the transcription factors NRF2 and activating transcription factor 4 (ATF4)." (PMID 33294126, 2020). "Furthermore, BRD4 expression was positively related to GPX4, SLC7A11, and SLC3A2 expression in pan-cancer patients." (PMID 30988278, 2019). "When exposed to paclitaxel, cancer cells activated the EIF2AK3/EIF2AK4‐pEIF2S1‐ATF4 axis and maintained redox homoeostasis by inducing expression of the major antioxidant enzymes HMOX1, SHMT2 and SLC7A11." (PMID 31211507, 2019). "In many cancer cells, amino acid transporters are upregulated to enable rapid cell growth and are therefore potential drug targets e.g. as SLC1A5, SLC6A15, SLC7A5, and SLC7A11." (PMID 29868606, 2018). "Interestingly, chemoresistant cancer cells markedly overexpress GPX4 and SLC7A11." (PMID 41596341, 2026). "Notably, in SLC7A11‐high cancer cells, the absence of adequate glutamine or inhibition of relevant enzymes primarily impedes cell growth rather than inducing substantial cell death." (PMID 39354653, 2025). "Also, silencing LDHB did not decrease SLC7A11 expression in KRAS wild-type cancer cells; in fact, an increase in SLC7A11 was observed in HT1080 cells after LDHB silencing, but LDHB silencing still sensitized KRAS wild-type cancer cells to GPX4 inhibition." (PMID 40090955, 2025). "Since METTL3 can negatively regulate the pGL-SLC7A11 promoter reporter, it indicates that transcription factors are also involved in m6A-regulated transcription of SLC7A11.We found that GATA3 is involved in METTL3-regulated expression of SLC7A11 and ferroptosis in cancer cells." (PMID 39800682, 2025). "Thus, SLC7A11 and GCLC expression could be defined as a cancer signature of GAS41 amplification in NSCLC (KEAP1 and NFE2L2 WT)." (PMID 38514704, 2024). "SLC7A11 inhibitors have not achieved therapeutic benefit for cancer patients yet in several clinical trials, which might be due to that cysteine import compensates intracellular cysteine levels after inhibiting SLC7A11." (PMID 39079386, 2024). "Notably, certain types of cancer, such as Kirsten rat sarcoma viral oncogene (KRAS)-mutant lung adenocarcinomas and pancreatic cancer, are highly sensitive to the intervention targeting SLC7A11." (PMID 39624080, 2024). "In addition, bioinformatics analyses showed that SLC7A11 and GPX4 expression (two critical regulators of ferroptosis) are increased in LUAD and LUSC patients and their expression were correlated with the individual cancer stages of LUAD and LUSC." (PMID 38561419, 2024). "Since SLC7A11 is not essential in normal tissues but is highly expressed in multiple cancers, including lung and kidney cancers, it represents a promising target for novel cancer therapies." (PMID 38886311, 2024).
cancer (continued). "Therefore, it suggests that SLC7A11 and GPX4 may serve as novel therapeutic targets for cancer therapy." (PMID 37807410, 2023). "However, we found that treatment with the iron chelator deferoxamine (DFO) failed to rescue H2O2-induced cell death in SLC7A11-high cancer cells used in our studies; as a control, DFO treatment abolished RSL3-induced ferroptosis in these cell lines." (PMID 37339981, 2023). "Results showed that the expression of GCLC, SOD1 and SLC7A11 in ML385 treatment groups significantly decreased compared to that of the control groups, and the reduced antioxidant capacity re-increased the oxidative stress levels, resulting in the slowing-down of cancer cell proliferation." (PMID 37682862, 2023). "In cancer cells, the BRD4 inhibitor JQ1 induces ferroptosis by enhancing the expression of an HDAC named SIRT1, which decreases the H3K27ac level at upstream of BRD4, ultimately affecting the recognition of acetylation sites on the histones at GPX4 and SLC7A11 genes." (PMID 37229485, 2023). "On the other hand, overexpression of SLC7A11 leads to increase of cystine uptake, accompanied by augmentation of glutamate export and NADPH consumption (due to NADPH-dependent reduction of cystine to cysteine), which forces cancer cells to be highly dependent on pentose phosphate pathway (PPP)." (PMID 35053507, 2022). "cytotoxic-T-cell-driven immunity promotes ferroptotic cell death in cancer cells, which is observed in T cell-driven antitumor immune response launched by immunotherapy with ICIs, mechanistically because of IFN-γ launching the JAK-STAT1 pathway and reducing SLC3A2, SLC7A11." (PMID 35432535, 2022). "Additionally, exposure to mifepristone downregulated the expression of several apoptotic genes, including BIRC5 and HELLS, while increased the expression of SLC7A11, a transporter involved in ferroptosis, an iron-dependent cell death that has been shown to be regulated in PDAC and other cancers." (PMID 36359879, 2022). "However, the effectiveness of the SLC7A11 inhibitors or cyst(e)inase has been established in many preclinical studies but has not reached the stage of clinical trials for cancer patients." (PMID 36552652, 2022). "Additionally, immunotherapy activated CD8+ T cells can induce ferroptosis in cancer cells by interferon gamma-mediated downregulation of the two subunits of system Xc−, solute carrier family 7 member 11 (SLC7A11) and SLC3A2, leading to a decrease in the antioxidant capacity of cancer cells." (PMID 33499222, 2021). "In addition, we identified SLC7A11 as a new UFMylation substrate and found that targeting the UFM1/SLC7A11 pathway could be a promising cancer treatment strategy." (PMID 34162423, 2021). "Fourth, the cancer‐promoting feature of SLC7A11 was not evaluated in vitro using a xenograft model." (PMID 34761566, 2021). "To test SLC7A11 as a response prediction marker for APR-246 sensitivity in pediatric nervous system tumors, we first performed an in silico data analysis of responsive and less-responsive cell lines of the whole Cancer Cell Line Encyclopedia (CCLE), including all cell lines." (PMID 34503286, 2021). "In addition, NRP1, CD276, and VSIR showed obvious positive correlation with SLC7A11 expression in most cancers, although the drugs targeted at these checkpoints have not been applied in clinic." (PMID 34938318, 2021). "Thus, the SLC7A11/selenide production/SEPHS2 detoxification axis illustrates a kitchen sink mechanism of toxicity, and at the same time suggests potential advantages of a metabolite poisoning strategy to kill cancer cells." (PMID 32709924, 2020).
cancer (continued). "Thus, xCT/SLC7A11 expression, in conjunction with environmental cystine, is necessary and sufficient to increase glutamine catabolism, defining important determinants of glutamine anaplerosis and glutaminase dependence in cancer." (PMID 28826492, 2017). "Early hypotheses regarding ferroptosis emerged from observations in nutrient-deprived cancer cells and from studies on “oxytosis”—a phenomenon where neurons die due to glutamate toxicity coupled with inhibition of the amino acid antiporter SLC7A11/xCT/system xc−." (PMID 40642182, 2025). "In addition, the expression of GPX4 and SLC7A11 in platinum‐resistant ovarian cancer cell lines SKOV3 and A2780 can be downregulated by supermagnetic nano‐iron oxide (SPIO) human serum, which can increase the level of ROS in cells and induce ferroptosis in cancer cells." (PMID 40821694, 2025). "Studies have confirmed that GLUT inhibitors can induce disulfur status and cell death in cancer cells with high SLC7A11 expression, and cancer cell disulfidptosis may be a key factor in the therapeutic effect of GLUT inhibitors in the treatment of tumors with high SLC7A11 expression." (PMID 38729953, 2024). "Interestingly, although many ferroptosis regulators such as GPX4, SLC7A11, and FTH1 are obviously increased in certain cancers compared with normal tissues, the treatments targeting these regulators might vary in effectiveness across different cancers." (PMID 38169587, 2024). "Furthermore, SLC7A11 inactivation is related to ferroptosis (an iron-dependent, nonapoptotic cell death triggered by an impaired antioxidant system) via AMPK signaling; thus, SLC7A11 may be a new potential target for overcoming cancer resistance." (PMID 37174663, 2023). "In addition, studies have shown that CD44 can stabilize the SLC7A11 subunit on the cell membrane, promote the growth of CRC cells, and increase SLC7A11-dependent protection from reactive oxygen species (ROS), thus enabling cancer cells to escape from oxidative damage." (PMID 36672372, 2023). "Thus, disulfidptosis could be induced in cancer cells regardless of SLC7A11 expression, and targeting disulfidptosis with glucose inhibitors offers new potential for cancer treatment." (PMID 37318660, 2023). "In a recent study, Yangyi Zhang 135 demonstrated that chronic cadmium exposure could promote cancer cell growth and inhibit ferroptosis by upregulating lncRNA OIP5-AS1 expression, and lncRNA OIP5-AS1 acted as a ceRNA that sponges miR-128-3p to increase the level of SLC7A11." (PMID 35342359, 2022). "Although several studies evaluated the function of SLC7A11 and SLC1A5, the role of some SLC proteins in cancer is not studied well." (PMID 38705513, 2024). "Only SLC7A11, TFAP2A, and LIMS2 are commonly regulated by the MDF in carcinomas (not in GBM), but only if the direction of the correlation was inversed for PAAC, whose impact on OS was also inverse." (PMID 32806596, 2020). "However, cancer cells counteract this by enhancing antioxidant defenses, notably through GPX4, SLC7A11, and FSP1, which mitigate ferroptosis and sustain cell survival." (PMID 39935430, 2025). "SLC7A11 expression was found to be a negative correlation with the expression of CD8+ T cells and IFN-γ in tumors, and down-regulation of SLC7A11 can improve the prognosis of cancer patients." (PMID 36712497, 2023). "Meanwhile IR may inhibit ferroptosis by inducing the expression of SLC7A11 and GPX4 as a negative feedback regulatory pathway to induce radiotherapy resistance in cancer cells." (PMID 36505465, 2022).
infection (39 papers, 2010 to 2026). The state of being infected such as from the introduction of a foreign agent such as serum, vaccine, antigenic substance or organism. "In order to determine if LS infection was susceptible to the pharmacological inhibition of SLC7a11, Hepa1-6 cells were infected with P. yoelii sporozoites, then treated with Erastin begining at 1.5 h post-infection." (PMID 31065106, 2020). "Western blotting analysis revealed that PPRV infection suppressed the expression of SLC7A11 and GPX4, while increasing ACSL4 expression in EECs in a dose- and time-dependent manner." (PMID 40197059, 2025). "The results demonstrated that the mRNA levels of SLC7A11 in both brain and liver tissues were significantly reduced after 12 h of infection." (PMID 40422259, 2025). "At both the transcriptional and translational levels, T. gondii infection (MOI 1 or 10, 24 h post-infection) significantly upregulated SLC7A11, ACSL4, and COX2 compared to uninfected controls." (PMID 40667873, 2025). "Instead, it suggests that the degradation of SLC7A11 is an integral part of the infection process itself." (PMID 40198689, 2025). "It has been reported that upregulation of SLC7A11 by KSHV-encoded miR-K12-11 facilitates KSHV dissemination and de novo infection." (PMID 38470932, 2024). "The mRNA transcription level of antioxidant downstream genes Solute Carrier Family 7 Member 11 (SLC7A11) decreased (p < 0.05) after DK/212 infection." (PMID 38542289, 2024). "The results of our in vivo experiments show that GFAP expression was downregulated whereas SLC7A11 was upregulated after TgCtwh3 infection." (PMID 37651502, 2023). "The upregulation of SLC7A11 exacerbates the export of cellular glutamate after TgCtwh3 infection in vivo." (PMID 37651502, 2023). "To further examine the regulation between TERT and SLC7A11, we employed lentiviral infection to either overexpress or suppress TERT levels in MLE-12 cells." (PMID 34716298, 2021). "To probe the capacity of the SLC7a11 pathway to regulate Plasmodium liver stage infection, we generated knockdown hepatoma cell lines for several components of the pathway." (PMID 31065106, 2020). "However, S. aureus infection induced only marginal up-regulation of SLC7A11 expression in CD11b+Ly6G+ neutrophils by day 14 post-infection, while expression levels remained unchanged in CD11b+Ly6C+ monocytes throughout the entire infection course." (PMID 38725861, 2024). "As expected, we found that the intracellular levels of MDA were significantly decreased in macrophages after 12 hours of infection but the effect could be blocked by erastin treatment or si-Slc7a11." (PMID 38725861, 2024). "Notably, flow cytometry data also revealed a substantial increase in SLC7A11 expression in neutrophils at day 14 post-infection, warranting further investigation into SLC7A11's role in regulating neutrophils function during S. aureus infection." (PMID 38725861, 2024). "The results showed that, compared to the control group, the down-regulation of antioxidant gene mRNA caused by DK/212 infection was inhibited after interference with the expression of the TRIM21 gene, and the protein level of NRF2, SLC7A11, and GPX4 was increased." (PMID 38542289, 2024). "Given that macrophage antimicrobial responses typically involve subjecting pathogens to oxidative stress, the sustained expression of Slc7a11 upon infection with UTI89 may be required to maintain glutathione levels and cytoprotection during stress responses." (PMID 25410299, 2015). "Consistent with a previous report that E. coli inhibited SLC7A11/GPX4 signalling in BMECs, infection with E. coli resulted in the inhibition of SLC7A11 and GPX4 expression in endometrial tissue and BEECs, which may be responsible for the imbalance in redox homeostasis in this study." (PMID 41413615, 2025). "Additionally, SLC7a11 inhibitors Erastin and Sorafenib reduce infection." (PMID 31065106, 2020).
infection (continued). "Conversely, the expression of solute carrier family members SLC7A11, glutathione peroxidase 4 (GPX4), and the iron efflux pump protein FPN1/SLC40A1 was downregulated, with this effect alleviated in the TbΔirp2 infection group." (PMID 40034497, 2025). "The results displayed that RES significantly increased the mRNA levels of Nrf2 and its target genes, including γ-GCS, SLC7A11, and GSR, compared with the ASFV-WT infection group at 12, 24, and 48 hpi." (PMID 39964001, 2025). "Our data showed that both biotypes of BVDV infection suppressed the expression of Nrf2, SLC7A11, and GPX4 in MDBK cells compared to mock-infected cells in a post infection time-dependent manner." (PMID 38226812, 2024). "Relative to Adv-GFP, either Adv-ATF4 or Adv-NRF2 induced Slc7a11 mRNA in WT and Atf4Δ hepatocytes, but the response to Adv-ATF4 was suppressed in Nfe2l2−/− hepatocytes, a defect that was overcome by Adv-NRF2 infection." (PMID 36996941, 2023). "Conversely, levels of the cysteine-glutamate antiporter SLC7A11 (XCT) exhibited a significant increase in cKO BMDMs following infection." (PMID 34085925, 2021). "albicans infection induced ferroptosis in vaginal tissues and macrophages, as manifested by lipid ROS accumulation, Fe2+ overload, GSH depletion, downregulation of GPX4 and SLC7A11, upregulation of ACSL4, 4-HNE, and MDA, and mitochondrial structural damage." (PMID 42072050, 2026). "Our findings revealed that after PbA infection, ACSL4 expression increased in splenocytes, while SLC7A11 and GPX4 expressions significantly decreased, indicating that malaria infection leads to iron homeostasis imbalance and elevated lipid peroxidation in the host." (PMID 41422632, 2025). "Pathogen infection or viral proteins induce the release of inflammatory cytokines such as IL-6 and TNF-α, which subsequently suppress key antioxidant proteins like GPX4 and SLC7A11, initiating ferroptosis." (PMID 41479924, 2025). "Interestingly, the protein level of SLC7A11 in BMDMs was not altered at 6 hours post-infection." (PMID 38725861, 2024). "Although SLC7A11 and FTH1 expression also increased at 1 h post-infection, this increase was not significant." (PMID 41413615, 2025). "We found that DDIT4, CTH, RELB, and SLC7A11, but not NDRG1 and CHAC1, increased in gastric tissues at 4 months post-infection (MPI)." (PMID 32457731, 2020). "By contrast, MC1-R protein was induced almost immediately after infection of Mel1700 cells, but there was no appreciable impact on the already high baseline level of TRP-1; instead, there was a virus-induced increase in mRNA for MC1-R, POMC (the precursor of α-MSH), and xCT (gene name SLC7A11)." (PMID 24701351, 2014).
neurodegenerative disease (11 papers, 2011 to 2026). A disorder of the central nervous system characterized by gradual and progressive loss of neural tissue and neurologic function. "In certain neurodegenerative diseases, the expression level of SLC7A11 is markedly higher than that in normal cells." (PMID 38886311, 2024). "Its relationship with SLC7A11 may shed light on how it promotes ferroptosis in neurodegenerative diseases." (PMID 41561226, 2026).
metabolic disorder (9 papers, 2019 to 2025). "Increasing evidence shows that SLC7A11/xCT, one of the vital regulators of intracellular antioxidants, has become a focal point for the synchronous regulation of these metabolic disorder‐associated PCDs." (PMID 40900810, 2025). "Ferroptosis, driven by iron-dependent lipid peroxidation through the Fenton reaction and inactivation of the GPX4/Nrf2/SLC7A11 axis, disrupts spermatogenesis under conditions of oxidative stress, environmental toxin exposure, or metabolic disorders." (PMID 40331931, 2025). "Here, we report that DUXAP8 induced cystine depletion, substantial enhancement of lipid peroxidation, and ferrous ion metabolic disorder in HCC cell lines, while SLC7A11 could reverse the effects of DUXAP8 on ferroptosis in HCC." (PMID 37337470, 2023).